MIR4315-2 (microRNA 4315-2)
Synonyms: hsa-mir-4315-2
Gene: MicroRNA gene on chromosome 17 (64,822,030 to 64,822,102, reverse strand). Ensembl gene ENSG00000284172.
Homologues: Paralogues in human: MIR4315-1 (100% identical).